MEG3 (maternally expressed 3)
Diseases named in the same sentence as MEG3 in open-access papers (continued):
Sharing a sentence is not in itself a finding about the gene and the disease.
asthma (continued). "The results indicate that lncRNA MEG3 is involved in the mechanism of asthma, while the specific roles and regulatory mechanisms remain to be further investigated." (PMID 38824534, 2024). "Earlier studies found reduced expression of MEG3 in the circulating CD8+ T cells of patients with severe asthma." (PMID 36726728, 2023). "Our findings in this current study supports the notion that reduced MEG3 expression favors asthma development." (PMID 36726728, 2023). "An early study compared the profile of lncRNA expression in circulating CD8+ T cells from asthma patients and healthy controls and found MEG3 expression was significantly lower in patients with severe asthma than healthy controls." (PMID 36726728, 2023). "Better understanding of the biology behind the roles of MEG3 in asthma warrants further investigation." (PMID 36726728, 2023). "The rs7158663 genotypes-MEG3 expression-asthma relationship is therefore biologically meaningful and plausible." (PMID 36726728, 2023). "Logistic regression analysis showed that inflammatory phenotype, the course of disease, and serum MEG3 level were independent prognostic factors for the recurrence of asthma (Feng, Yang & Yan, 2020)." (PMID 36726728, 2023). "We then analyzed the distributions of MEG3 genotypes among asthma patients within different symptom groups." (PMID 36726728, 2023). "Lastly, the mRNA levels of MEG3 are lower in asthma patients than in healthy controls (Feng, Yang & Yan, 2020)." (PMID 36726728, 2023). "A recent study (Feng, Yang & Yan, 2020) reported that serum MEG3 level was significantly lower in asthma patients than in healthy controls and was the lowest in the most severe asthma patients." (PMID 36726728, 2023). "They found that MEG3 expression levels were upregulated and negatively associated with miRNA-17 expression in CD4+ T cells of patients with severe asthma." (PMID 35769905, 2022). "There is increasing evidence that the lncRNA–miRNA–mRNA axis is involved in asthma pathogenesis, for example, MEG3 and MALAT1 are involved." (PMID 36463267, 2022). "Qiu et al24 reported that the lncRNA MEG3 functions as ceRNA and attenuates miR‐17 to regulate the Th17/Treg balance in asthma pathogenesis." (PMID 35266286, 2022). "The lncRNA MEG3/miR-17/RORγt axis can affect Th17/Treg balance in asthma and provide a powerful basis for clinical treatment." (PMID 33013382, 2020). "Another study showed that expression of the lncRNA MEG3 was reduced in circulating CD8+ T cells in patients with severe asthma, in addition to 18 other lncRNAs." (PMID 30941157, 2019). "We aimed to find out the role and mechanism of lncRNA MEG3 in asthma." (PMID 38824534, 2024). "Recent research have found lncRNA MEG3 was significantly increased in asthmatic patients, suggesting lncRNA MEG3 may be involved in the occurrence of asthma." (PMID 38824534, 2024). "Besides, the expression of lncRNA MEG3/miR-143-3p/FGF9 in asthma patients and its correlation with clinical pathological parameters also need further clarification." (PMID 38824534, 2024). "There have been strong evidences supporting that MEG3 plays a role in asthma development." (PMID 36726728, 2023). "Furthermore, there was a significant inverse correlation between serum MEG3 expression and the course of asthma (r = −0.666, P < 0.001) (Feng, Yang & Yan, 2020)." (PMID 36726728, 2023). "The variant genotype carriers had significantly lower serum MEG3 expression, consistent with prior reports of downregulation of MEG3 expression in asthma patients and providing biological explanation for the observed associations between variant genotypes and increased asthma risks." (PMID 36726728, 2023). "Furthermore, the AG and AA genotype carriers had lower serum MEG3 expression level than the GG genotype carriers, consistent with the reported downregulation of MEG3 in asthma patients." (PMID 36726728, 2023). "Meg3 also affected the Treg/Th17 balance in asthma patients via miR-17/RORγt axis." (PMID 31761787, 2019).
asthma (continued). "However, it is unclear whether lncRNA MEG3 plays an important role in asthma through regulating miR-143-3p." (PMID 38824534, 2024). "However, specific roles and regulatory mechanisms of lncRNA MEG3 in asthma is still unclear." (PMID 38824534, 2024). "Therefore, the microRNA sponge effect of MEG3 may be one of the biological mechanisms responsible for the involvement of MEG3 in asthma development." (PMID 36726728, 2023). "Thus, reduced expression of lnc-MEG3 could influence the development of Th2-low asthma symptoms." (PMID 41156032, 2025). "We established a cellular model of asthma by inducing human airway smooth muscle cells (HASMCs) with PDGF-BB, and detected levels of lncRNA MEG3, miR-143-3p and FGF9 in HASMCs through qRT-PCR." (PMID 38824534, 2024). "Additionally, miR-17 was detected as a target of MEG3, and it could suppress the Th17 response or promote it by targeting RORyt, suggesting that MEG3/miRNA-17/RORyt axis plays a role in the Th17 imbalance in asthma." (PMID 35769905, 2022). "Therefore, we can assume that MEG3/miRNA-17/RORyt axis could be a biomarker of asthma severity." (PMID 35769905, 2022). "However, the relationship between lncRNA MEG3 and miR-143-3p in asthma has not been reported." (PMID 38824534, 2024).
leukemia (17 papers, 2013 to 2026). A malignant (clonal) hematologic disorder, involving hematopoietic stem cells and characterized by the presence of primitive or atypical myeloid or lymphoid cells in the bone marrow and the blood. "Aberrant DMR methylation is observed in several leukaemias, including hypermethylation of the MEG3-DMR in AML, MDS and myeloma, and loss of IG-DMR imprinting is associated with increased MEG3 and 14q32 miRNA expression in acute promyelocytic leukaemia." (PMID 37169950, 2023). "MEG3, a lincRNA implicated in leukemia, was examined following microarray detection experiment of enriched transcripts in a mouse inner ear library." (PMID 24391537, 2013). "The association of lncRNAs with several subtypes of leukemia, such as MEG3, IRAIN, and UCA1 related to AML and ANRIL, LUNAR1, in ALL, increase the possibility to use them as biomarkers for the diagnosis, prognosis, and treatment (to provide a target) for the different subtypes of this disease." (PMID 30744139, 2019). "Other studies have established miR-147 and a lncRNA MEG3 target that is closely tied to the proliferative activity and apoptotic death of leukemia cells in vitro." (PMID 38510653, 2024). "Lower MEG3 levels have been found in advanced stages of leukemia while, to the contrary, miR-21 was found to be over-expressed which was able to interact with MEG3 by decreasing its expression." (PMID 34065882, 2021). "Future studies will be necessary to better understand the role of Meg3 in development and maintenance of leukemia." (PMID 30765776, 2019). "We used two lncRNA constructs, HOTAIR440, a segment of HOTAIR that contains the region involved in binding to EZH2, MEG3, a lncRNA involved in leukemias and a 50 nt long RNA with random nucleotide sequence." (PMID 30400675, 2018). "In our study, we show that loss of Meg3 alone did not lead to the development of leukemia or myeloproliferative diseases even in long-term experiments such as tertiary transplantations." (PMID 30765776, 2019). "In this context, lncRNAs such as GAS5, MEG3, CCND1, MORT, and LincRNA-p21 are downregulated in breast, lung, prostate, and renal cancers, as well as in leukaemia and lymphomas." (PMID 41597397, 2026). "For example, lncRNA MEG3, as a tumor suppressor of AML, its hypermethylation can lead to a decrease in DNMT3A expression, which in turn inhibits the occurrence of leukemia." (PMID 34694569, 2022). "Accumulating evidence suggests the opposing roles of these genes on growth and development are mirrored in leukemias, where DLK1 maintains cell stemness and enhances the proliferation of leukemic cells and MEG3 suppresses leukemogenesis and leukemic cell proliferation." (PMID 30876483, 2019).
gallbladder cancer (16 papers, 2018 to 2022). "In cholangiocarcinoma and gallbladder cancer, MEG3 stimulated NF-κB signaling pathway and triggered apoptosis by sponging miR-361-5p expression and activating TNF receptor-associated factor 3 (TRAF3)." (PMID 36551518, 2022). "LncRNA MEG3 suppresses the progression of gallbladder cancer by promoting the ubiquitination of EZH2 to regulate LATS239." (PMID 33568633, 2021). "In Gallbladder cancer, lncRNA MEG3 performs functions by regulating the stability of EZH2 to regulate the downstream target gene LATS2 and thereby inhibits invasion and proliferation." (PMID 34131399, 2021). "For example, the expression of MEG3 in gallbladder carcinoma tissues is significantly lower than that in normal tissues." (PMID 32277605, 2020). "MEG3 suppresses cell proliferation and promotes cell apoptosis in gallbladder cancer, and up-regulating MEG3 may be applied for inhibiting the deterioration of the tumor." (PMID 33665015, 2021). "Ectopic overexpression of MEG3 effectively inhibits the growth of gallbladder cancer cells." (PMID 34869051, 2021). "In this study, we revealed MEG3-mediated targeting of EZH2 to ubiquitination and degradation, which is consistent with a previous study in gallbladder cancer." (PMID 35256601, 2022). "Long noncoding RNA MEG3 regulates LATS2 by promoting the ubiquitination of EZH2 and inhibits proliferation and invasion in gallbladder cancer." (PMID 34789260, 2021). "MEG3 is a lncRNA closely related to EZH2, and MEG3 attenuates EZH2 by increasing its ubiquitination in gallbladder cancer." (PMID 33061817, 2020). "Previous studies have reported that lncRNA MEG3 promotes the ubiquitination of EZH2 and inhibits the proliferation and invasion of gallbladder carcinoma cells by regulating LATS224." (PMID 32157157, 2020). "MEG3 and UCA1 could both target Enhancer of Zeste Homolog 2 (EZH2), despite their differential roles in gallbladder cancer." (PMID 31297033, 2019). "Furthermore, MEG3 could activate apoptotic cascade in laryngeal cancer by sponging miR-23a and promotes apoptotic protease activating factor-1 (APAF-1) expression, and in gallbladder cancer by promoting EZH2 ubiquitination/proteasomal degradation." (PMID 36551518, 2022).
lung adenocarcinoma (16 papers, 2015 to 2026). A carcinoma that arises from the lung and is characterized by the presence of malignant glandular epithelial cells. "TMED2, MOESIN, DPYSL2, and LncRNA MEG3 have been discovered to enhance the occurrence and development of patients with lung adenocarcinoma via several immune-related regulatory mechanisms." (PMID 35354488, 2022). "By contrast, MEG3 expression was significantly higher in LUAD (lung adenocarcinoma) than in normal tissue." (PMID 34220951, 2021). "Our previous study also demonstrated that downregulation of the lncRNA MEG3 contributes to cisplatin resistance of lung adenocarcinoma." (PMID 32477939, 2020). "In the K mouse model of lung adenocarcinoma, the Dlk1-Dio3 locus, including the miRNA cluster and Rtl1, Meg3 and Dlk1, was found upregulated in lung tumors compared to normal lung tissue." (PMID 30190790, 2018). "This hypothesis proposes MEG3 as a cell-specific angiogenesis promotor, as Lui and colleagues detected a significant downregulation of MEG3 in lung adenocarcinoma." (PMID 32992718, 2020). "Serum EV-miR-21-5p, miR-486-3p, MEG3 and XIST levels may correlate with disease progression and treatment response in patients with ALK-translocated lung adenocarcinoma prescribed ALK-TKI treatment." (PMID 30658414, 2019). "The lncRNA maternally expressed 3 (MEG3) reported to be correlated with tumorigenesis, was also included in this region and was identified to be up‐regulated in the mouse lung adenocarcinoma tissues (corresponding to the lncRNA NONMMUT015697) and regulated by kras in our results." (PMID 31410985, 2019).
thyroid cancer (16 papers, 2017 to 2025). "The link between MEG3 and metastasis has also been confirmed by clinical samples from thyroid cancer (TC) patients showing that MEG3 downregulation was associated with lymph node metastasis." (PMID 36551518, 2022). "Overall, our analysis identifies MEG3 expression as highly associated with LNM in thyroid cancer with a potential role in contributing to metastatic potential via its expression in CAFs." (PMID 36231143, 2022). "MEG3 inhibits migration and invasion of thyroid cancer cells by acting on Rac1 and is linked with lymph node metastasis." (PMID 32596158, 2020). "Interestingly, MEG3 was shown to downregulate TGFβ receptor 1 in fibroblasts by Mondal, which may appear discordant with our finding CAFs expressing MEG3 are associated with LNM-positive thyroid cancer since TGFβ signaling is needed for fibroblast activation." (PMID 36231143, 2022). "An inverse correlation between MEG3 and Rac1 was observed, supporting the role of MEG3 as a tumor suppressor in thyroid carcinoma." (PMID 41150811, 2025). "Our findings characterize the region’s epigenetic signature in thyroid cancer, uncovering distinctive DNA methylation patterns, particularly within CpG islands on the lncRNA MEG3-DMR, which potentially account for its downregulation in tumors." (PMID 38920632, 2024). "To determine the cell type within the thyroid cancer tumor environment that expresses MEG3, we aimed to use existing single-cell RNA-sequencing (scRNA-Seq) data from thyroid cancer samples with high metastatic and invasive potential." (PMID 36231143, 2022). "To determine the cell types that express MEG3 in aggressive thyroid cancer, we analyzed existing scRNA-seq data from anaplastic thyroid cancer." (PMID 36231143, 2022). "Furthermore, the expression of MEG3 was highly predictive of tumor infiltration with cancer-associated fibroblasts, and single-cell RNA-sequencing data revealed the expression of MEG3 was isolated to cancer-associated fibroblasts (CAFs) in the most aggressive form of thyroid cancers." (PMID 36231143, 2022). "For thyroid cancer cells resistant to 131I, low expression of MEG3 means increased expression of miR-182 and promotion of cell proliferation, which is detrimental to the treatment effect of 131I for thyroid cancer." (PMID 36523500, 2022). "MEG3 targeted Rac1 and reduced its protein expression, resulting in suppressed primary thyroid cancer migration and invasion." (PMID 34290983, 2021). "Long non-coding RNA MEG3 has been a suggested as a biomarker for thyroid cancer and 131I radio-resistance." (PMID 33382739, 2020). "In human thyroid cancer cell lines, high levels of MEG3 can inhibit invasion and metastasis of thyroid cancer cells." (PMID 32596158, 2020). "This study showed that the Rac1 gene is negatively regulated by MEG3 at the posttranscriptional level in thyroid cancer." (PMID 32596158, 2020). "LncRNA MEG3 contributes to 31I I sensitivity by targeting miR-182 in thyroid carcinoma." (PMID 38006396, 2023). "Interestingly, the maternally expressed 3 (MEG3) acts as protective lncRNA inhibiting the migration and metastasis of thyroid carcinoma by repression of Rac1." (PMID 35447891, 2022). "Downregulation of lncRNA MEG3 was correlated with lymph node metastasis in primary thyroid cancer." (PMID 34290983, 2021). "Interestingly, signals indicating MEG3 predominately localize to CAFs in the high-grade subtypes of thyroid cancer, suggesting that changes to the stroma could enable metastatic behavior." (PMID 41154428, 2025). "Besides, MEG3 was closely related to 131I-sensitivity of thyroid carcinoma by sponging miR-182." (PMID 36551518, 2022). "Of note, in PTCs, the lncRNA MEG3 was shown to be highly expressed in thyroid cancers, with lymph node metastases compared with tumors without lymph node metastases." (PMID 36077709, 2022). "However, the correlation between MEG3 expression and MMP-2 production in CAFs requires necessary further investigation and validation in thyroid cancers." (PMID 36077709, 2022).
thyroid cancer (continued). "For thyroid cancer cells resistant to 131I, low MEG3 expression is not good news." (PMID 36523500, 2022).
type 2 diabetes (16 papers, 2014 to 2024). "Genetic variants of MEG3 confer risk of type 2 diabetes in populations." (PMID 31195367, 2019). "Hypomethylation of MEG3- IG region could explain the association between MD and improvements of type 2 diabetes." (PMID 31052443, 2019). "For instance, MEG3 is discovered to be abnormally elevated in type 2 diabetes patients in the clinic and exacerbates insulin resistance by downregulating the miR-185-5p/Egr2 axis and upregulating Foxo1 expression." (PMID 36968595, 2023). "In addition, reduced expression of Dlk1-Dio3 miRNAs, specifically in islet β cells of human patients with type 2 diabetes mellitus (T2DM), has been associated with DNA hypermethylation at MEG3-DMR in the β cells from T2DM donors." (PMID 34062726, 2021). "The expression of MEG3 was also studied in PBMCs (peripheral blood mononuclear cells), and, again, its overexpression was showcased in patients affected by type 2 diabetes." (PMID 32545342, 2020). "In the recent years, mounting evidence has also revealed MEG3’s connection to type 2 diabetes and insulin resistance in the pancreas, diabetic microvascular dysfunction, and nephropathy." (PMID 32545342, 2020). "We screen 99 phenotypes for parent-of-origin effects and replicate the discoveries of 6 GWAS studies, confirming signals on body mass index, type 2 diabetes, standing height and multiple blood biomarkers, including the known maternal effect at the MEG3/DLK1 locus on platelet phenotypes." (PMID 36335127, 2022). "The MEG3-IG region may be an upstream regulator of the MEG3 DMR, which has been associated with type 2 diabetes." (PMID 31052443, 2019). "We have validated the usefulness of this method in the context of type 2 diabetes, first confirming reported differences in DNA methylation at the imprinted MEG3 locus, and by validation of previous genome-wide findings of CpG risk loci identified in type 2 diabetic human islets." (PMID 26236400, 2015). "Compared to control subjects, expression profiling of lncRNAs in PBMCs from type 2 diabetes patients showed significantly (p < 0.05) increased levels of HOTAIR, MEG3, LET, MALAT1, MIAT, CDKN2BAS1/ANRIL, XIST, PANDA, GAS5, Linc-p21, ENST00000550337.1, PLUTO, and NBR2." (PMID 30139387, 2018). "Compared to control subjects, expression levels of lncRNAs in PBMCs from type 2 diabetes patients showed significantly (p < 0.05) increased levels of HOTAIR, MEG3, LET, MALAT1, MIAT, CDKN2BAS1/ANRIL, XIST, PANDA, GAS5, Linc-p21, ENST00000550337.1, PLUTO, and NBR2." (PMID 30139387, 2018).